TERT (telomerase reverse transcriptase)
Diseases named in the same sentence as TERT in open-access papers (continued):
Sharing a sentence is not in itself a finding about the gene and the disease.
cancer (continued). "Thus, many cancer stem cells rely on TERT for telomere maintenance." (PMID 34830134, 2021). "There was a lack of matched primary sample analysis for cases with TERT fusion-positive metastases to determine whether the fusions represent early events in more aggressive cancers or later events associated with metastasis." (PMID 33741265, 2021). "Given the important biological function of the TERT and CLPTM1L genes, previous cancer fine-mapping efforts in this region, and the appearance of multiple association peaks for some of the cancers, it is plausible to assume that multiple variants in this region affect cancer risk independently." (PMID 34355204, 2021). "Furthermore, these data illustrate the need to analyze possible splicing aberrations that might influence subcellular localization of TERT in certain cell types or cancer, as shown here for intron 2 in the HCT116 cell line." (PMID 34083519, 2021). "Interestingly enough, TERT gene (telomerase reverse transcriptase) copy number gains and hotspot promoter mutations constitute the first recurrent oncogenic gain of function alterations in MPM, which are generally observed in ~10–15% of all cancer types." (PMID 32882916, 2020). "Further immunologic targeting of TERT may represent a promising new aspect in cancer treatment." (PMID 32810393, 2020). "The Cas9-based cancer therapy may further benefit from its multiplex targeting capacity, which enables simultaneous targeting multiple genes, for example telomerase genes (e.g., TERT), the ALT pathway genes, and other key ones to cancer cell survival pathways." (PMID 31963842, 2020). "Finally, we highlight the clinical implications of TERT activation and, describe future potential avenues to explore in order to better understand regulation of this key enzyme as well as its role in carcinogenesis and cancer prognosis." (PMID 32849278, 2020). "We examined, in cancer cells with monoallelic expression and WT TERT promoters, whether the non-expressed allele was selectively methylated." (PMID 32468444, 2020). "Furthermore, Huang and colleagues reported that some cancer cell lines show mono-allelic expression of TERT even in the absence of TERTp mutations." (PMID 32267900, 2020). "Thus, TERT pro-proliferative effect in cancer may in part come from enhancing tRNA expression, which in turn expands the translational capacity of malignant cells." (PMID 32599885, 2020). "Though any given gene may not be impacted in a large percentage of cancer cases (the more frequently SV-altered gene TERT involving <3% of cancers surveyed), the multiple genes involved leads to a large cumulative effect in terms of absolute numbers of patients." (PMID 32024823, 2020). "TERT mutations may be a potential biomarker for anti‐CTLA4 treatment, but not programmed cell death‐1 (PD‐1)/programmed cell death‐L1 (PD‐L1) blockade and combination treatment across pan‐cancer types." (PMID 32810393, 2020). "However, cancer cells can also exhibit monoallelic expression of TERT even in the absence of C228T/C250T promoter mutations." (PMID 32468444, 2020). "This suggests that TERT rearrangement could be a critical step in cancer development." (PMID 33329574, 2020). "However, given that the amount of telomerase activity a cell needs to overcome senescence corresponds to as low as 1% of TERT expression level in cancer, TERT likely has pro-malignant functions that are independent from its canonical role in telomere extension." (PMID 32599885, 2020). "As such, inhibiting TERT may provide a universal therapy for treating a wide spectrum of cancers." (PMID 31963842, 2020). "Therefore, inactivating TERT has been considered to be a promising means of cancer therapy." (PMID 31963842, 2020). "TERT promoter mutations may also be detected in urinary liquid biopsies from patients with no obvious evidence of cancer." (PMID 32533903, 2020).
cancer (continued). "In recent years, TERT has been reported to mediate many molecular events independently on its reverse transcriptase activity, which include activation of the Wnt/β-catenin signaling, induction of angiogenesis, regulation of DNA damage response, and inhibition of apoptosis in cancer development." (PMID 33239622, 2020). "Thus, an increase in TERT copy number could result in increased expression of TERT thus reestablishing telomerase activity in cancers." (PMID 32674474, 2020). "This literatures suggests that TERT-targeted antisense oligonucleotide, which selectively binds and targets only a portion of TERT in cancer, may exert a pro-apoptotic effect through silencing of the non-canonical function of TERT, thus telomere length is unaffected." (PMID 31035374, 2019). "Importantly, through the interaction of TERT with the Wnt/β-catenin and the NF-kB signaling pathways, the expression of telomerase may affect cancer invasiveness and metastasis." (PMID 31772219, 2019). "Importantly, the phosphatase and tensin homolog (PTEN) and Ras association domain family 1A, the two TSGs silent due to their promoter hypermethylation in these cancer cells, displayed corresponding alterations in their expression—up and down in TERT-depleted and over-expressed cells, respectively." (PMID 31284662, 2019). "Furthermore, TERT derepression has been demonstrated to promote escape of cancer cells from OIS." (PMID 31391125, 2019). "Mutations of the TERT promoter induce the formation of a consensus binding site for ETS (E-twenty-six) transcription factors that leads to increased gene expression, thus inducing telomerase activation, inhibition of the physiological telomere shortening, and immortalization of cancer cells." (PMID 30915113, 2019). "Therefore, the question arises about whether these extratelomeric functions of TERT operate in cancer cells, and above which threshold." (PMID 31911897, 2019). "Therefore, many cancers show changes in TERT splicing patterns." (PMID 31911897, 2019). "Collectively, these studies illustrated that human TERT promoter can endow cancer specificity to the oncolytic adenovirus through transcriptional regulation of the E1A gene, and that the potency of these vectors can be further improved through genetic modification of the human TERT promoter." (PMID 31035374, 2019). "Therefore, TERT plays a pivotal role in cancer by bridging various regulatory machinery." (PMID 31179925, 2019). "However, different pathways negatively regulated expression of TERT in different cancers." (PMID 29614790, 2018). "In addition, hTR levels are in excess over telomerase RNP complexes in cancer cells, indicating that a pool of TERT-free hTR might assemble into alternate RNP complexes both in normal and transformed cells." (PMID 30355447, 2018). "Hence, novel TERT-based therapeutic strategies that can elicit relatively rapid and sustained effects could have significant impact on cancer treatment." (PMID 29695835, 2018). "The mechanism of TERT upregulation in cancer has largely remained unknown to date." (PMID 29693015, 2018). "Interestingly, the functional miR-128 binding site in TERT mRNA, is conserved between TERT and the other cellular reverse transcriptase encoded by Long Interspersed Elements-1 (LINE-1 or L1), which can also contribute to the oncogenic phenotype of cancer." (PMID 29568354, 2018). "Overall, the most characterized TERTp hypermethylation at specific CpG islands, also named as THOR (TERT hypermethylated oncological region), has been reported to have diagnostic and prognostic value in prostate, NOS and pancreatic (exocrine and endocrine, NOS) cancers." (PMID 29751586, 2018). "TERT may therefore play an important role in cancer pathogenesis." (PMID 28060765, 2017). "However, other studies have highlighted that cancer cis-regulatory mutations are usually not recurrent across patients, except for a few exceptions such as the TERT promoter mutation." (PMID 28854983, 2017).
cancer (continued). "While TERT is reactivated in the broad range of cancers, not all cancers possess mutations in the TERT promoter, suggesting that other mechanisms such as chromosomal rearrangements may play a role in TERT activation." (PMID 28264499, 2017). "In ESCC, TERT-mediated activation of the Wnt and NF-κB signaling pathways and subsequent enhanced expression of target genes may play a direct role in facilitating cancer-promoting functions, such as proliferation and resistance to apoptosis." (PMID 29137437, 2017). "The mechanism underlying cancer-specific telomerase activation/TERT expression has been extensively studied, and recent findings showed that HCC tumors frequently bear activating mutations in the TERT proximal promoter (−124 and −146 bp from the ATG, so-called C228T and C250T, respectively)." (PMID 28416747, 2017). "Thus, Nault and coworkers have reported in some of these patients the clonal integration of adeno-associated virus type 2 (AAV2) at the level of some cancer driver genes, including CCNA2 (cyclin 2), TERT, CCNE1 (cyclin E1), TNSF10 and KMT2B, inducing overexpression of the target genes." (PMID 28930164, 2017). "Taken together, the germline TERT genetic background may significantly affect the onset of TERT promoter mutations in HCCs, which provides a better understanding of HCC-related TERT promoter mutations and telomerase regulation in cancer." (PMID 28416747, 2017). "Subgroup analysis by ethnicity suggested that individuals carrying TERT rs2736098 polymorphism from Asians but not among Europeans were more likely to exhibit an increased cancer risk, possibly because of the differences in genetic backgrounds among different populations." (PMID 29221218, 2017). "Therefore, high TERT expression in resected HCC might reflect potential cancer development in the surrounding liver." (PMID 28947783, 2017). "Furthermore, the methylated regions of the TERT promoter may differ among different types of cancer." (PMID 26870890, 2016). "Moreover, overexpression of TERT has been detected in a variety of cancer cells, including NPC." (PMID 26621837, 2016). "One possible explanation for these observations could be that incipient cancer cells, originating from rapidly self-renewing telomerase-competent cells, do not require TERT promoter mutations to regulate TL maintenance." (PMID 27323951, 2016). "In addition, TERT possesses many other important activities independent of its telomere-lengthening function, which has been implicated in cancer development and progression." (PMID 27561898, 2016). "We showed that overexpression of TPP1ΔOBRD, ATRX knockdown, DAXX deletion and TERT KO in telomerase-positive HTC75 cancer cells could promote ALT phenotypes by increasing APBs and C-circles, elongating telomeres and producing heterogeneous telomeres, which were very similar to ALT cells." (PMID 27578458, 2016). "Thus, the TERT gene clearly has multiple, pleotropic effects; 5′ variants affect promoter activity and TL, whilst more 3′ variants, affecting RNA splicing and a TERT silencer element, have roles in hormonal cancer development but not via changes to TL." (PMID 25986438, 2015). "Quantitative analysis of endogenous TERT expression levels, cellular telomerase activity and telomere lengths in cancer cell lines with or without these mutations has demonstrated that these mutations are associated with higher levels of telomerase and longer telomere lengths." (PMID 26553065, 2015). "In contrast, this approach will be challenging in cancer cells, as TERT mRNA levels, telomerase levels, and telomere length vary dramatically regardless of whether they carry any of the TERT promoter mutations." (PMID 26194807, 2015). "TERT may play an important role in the pathogenesis of cancer." (PMID 26042809, 2015).
cancer (continued). "Our finding suggests the TERT locus may influence the cancers development through variation in LTL." (PMID 24465473, 2014). "This may be a chance finding given that none of the associations remained significant after correcting for multiple tests, though such effects in opposite directions for different cancer types have been previously demonstrated in the TERT region and SNP rs401681 in particular." (PMID 24598796, 2014). "Finally, we did not obtain detailed information on cancer metastasis and survival, which further restricted the analysis of the roles of the hTERT rs2736098 G>A and TERT-CLPTM1L rs401681 C>T polymorphisms in ESCC progression and prognosis." (PMID 25007268, 2014). "In addition, TERT gene has frequently been activated in cancer and stem cells." (PMID 20969773, 2010). "This review explores the complex mechanisms by which TERT modulates key signaling pathways, such as NF-κB, AKT, and MYC, highlighting its role in driving autonomous cancer cell growth and resistance to therapy in B-cell malignancies." (PMID 40227701, 2025). "To investigate the interaction modes and binding affinities of GC-3,5-diGA and 1,2,4,6-GA-glc with shared targets involved in cancer and oxidative stress, we conducted systematic molecular docking analyses on four target proteins: FGF2, TERT, MMP9, and ABCG2." (PMID 40363725, 2025). "Several studies have established that TERT is a key regulator of TEL-TMM, as its activation is essential for maintaining telomere length in most cancers through telomerase activity." (PMID 40362411, 2025). "In addition, several studies revealed critical non‐canonical extra‐telomeric functions of TERT in various cellular processes, including cell proliferation and survival, DNA damage response, transcription, signal transduction, and metabolic regulation, both in normal and in cancer cells." (PMID 40213897, 2025). "Telomerase reverse transcriptase (TERT) is crucial for maintaining telomere length, which is often dysregulated in cancer." (PMID 40070565, 2025). "Here, the authors explore the locus within TERT intron 4, link it with a variable number tandem repeat (VNTR), and investigate its biological significance and role in cancer." (PMID 39956830, 2025). "The histone methyltransferase SMYD3 adds another layer of regulation by binding to the TERT promoter and activating its transcription through the methylation of histone H3K4 in both fibroblasts and cancer cells." (PMID 41301813, 2025). "Specifically, two loci—5p15.33 of TERT and 3q26.3 of TERC—are observed to be the most common amplifications within cancer types." (PMID 39858038, 2025). "Recent evidence suggests the existence of a multifaceted regulatory loop between TERT, NF-κB p65, and MYC in B-cell malignancies that contributes to cancer progression." (PMID 40227701, 2025). "Notably, VIM and TERT, which have shown diagnostic potential in BC studies, did not exhibit statistically significant differences in expression between the CRC and healthy control groups, indicating a divergence in the behavior of these markers between different cancer types." (PMID 40003943, 2025). "Then, TERT modulates glycolysis by regulating key enzymes like HK2, thereby promoting cellular energy production in cancer cells." (PMID 39940762, 2025). "TERT and HFE, which also affect both cancers, were expressed at low levels across hepatic cell types." (PMID 40823170, 2025). "TERC levels often exceed the number of assembled telomerase RNP complexes in cancer cells (approximately 1,150 TERC molecules in HeLa cells, compared to only about 500 molecules of TERT), suggesting the existence of unassembled TERC." (PMID 40025596, 2025).
cancer (continued). "Telomerase reverse transcriptase (TERT, −5.4 kcal mol−1) and thymidylate synthase (TYMS, −4.06 kcal mol−1) are both involved in sustaining the uncontrolled proliferation characteristic of cancer cells." (PMID 40733037, 2025). "An OCSCC cohort more than twice the size of the TCGA cohort allowed us to find additional cancer driver genes that are frequently affected in CNA-quiet OCSCC, notably PIK3CA, RAC1, and TERT, besides the previously established HRAS and CASP8." (PMID 39428388, 2024). "TERT expression was correlated with 17 genes encoding molecular targets of cancer therapeutics and may relate to differential survival patterns of TERT- positive and negative cancers." (PMID 38859942, 2024). "Telo-seq analysis recapitulated this striking difference in the telomere length distribution between TERT+ and ALT+ cancer cell lines and was highly reproducible between independent cancer cell line replicates." (PMID 38890299, 2024). "Recently, it has been reported that TERT interacts with various signaling molecules such as NF-κ B, c-MYC, β-catenin, and TCF-4 to increase cancer malignancy and promote cancer progression." (PMID 38927493, 2024). "To address the impact of both TMMs on telomeres, we performed Telo-seq on a set of five TERT+ and five ALT+ cancer cell lines." (PMID 38890299, 2024). "TERT also interacts with the TGF-β-responsive, enhancing cancer cell dissemination and disease progression." (PMID 39126110, 2024). "Several lines of evidence showed that the suppression of some genes or proteins, such as telomerase catalytic subunit TERT, AKT signaling, CTGF, HSP70, HSP90 and HSP27 significantly boosted the effects of hyperthermia-based anti-cancer treatments." (PMID 38419081, 2024). "Our lab performed a screening in TERT-P2A-GFP reporter cell line and found a natural product SC as a telomerase inhibitor for multiple cancer types." (PMID 38111043, 2023). "Based on our candidate selection process, three SFs are expected to be FL TERT promoters (HNRNPM in iPSCs; SRSF2 in both iPSCs and cancer cells; U2AF2 in cancer cells)." (PMID 37531400, 2023). "TERT can also directly binds to promoters with TCF elements and promote transcription, such as c-Myc and cyclin D1, which are highly expressed in cancer stem cells." (PMID 38111043, 2023). "Nine modulated microRNAs targeting the BRAF, TERT, and/or HLA-G genes were observed in PTC and involved with cancer-related signaling pathways." (PMID 37569841, 2023). "For example, we recently published that knockdown of SF3B4 induces reduction of FL TERT in NSCLC cells resulting in decreased telomerase activity, cell viability, and proliferation of cancer cells." (PMID 37531400, 2023). "These 1,670 genes involved well-established cancer-related genes, including MYC, MYB, BRCA2, ERCC4, and MET for s1 subtype and TERT, BCL2, and SUZ12 for s3 subtype." (PMID 36731467, 2023). "PGCC were found to express cancer-related markers such as α-methylacyl-CoA racemase (AMACR), or telomerase reverse transcriptase (TERT)." (PMID 37444476, 2023). "Duplications of a wild type sequence within the TERT promoter region, that include an ETS motif, have been identified in seven cancer types." (PMID 38033865, 2023). "Moreover, TERT-expressing cancer cells could be eliminated by oncolytic viruses." (PMID 37189709, 2023).